LOX (lysyl oxidase)
Diseases named in the same sentence as LOX in open-access papers (continued):
Sharing a sentence is not in itself a finding about the gene and the disease.
gastric cancer (continued). "For example, lysyl oxidase (LOX) is a monoamine oxidase associated with metastasis and adverse prognosis in gastric cancer." (PMID 36560848, 2023). "Another LOX inhibitor, namely, dextran sulfate, was shown to have anticancer effects in gastric cancer." (PMID 37509535, 2023). "The conflict between LOX expression and clinical parameters and prognosis value still exists in gastric cancer." (PMID 36202905, 2022). "In gastric cancer, LOX levels are correlated with the number of lymph node metastases, greater infiltration depth, and advanced tumor-node-metastasis stages." (PMID 36497411, 2022). "LOX is highly expressed in patients with gastric cancer, indicating poor prognosis and possibly promoting the progression of cancer cells through ECM receptor I interaction and TGF-β, Wnt, JAK–STAT, and mTOR signaling pathways." (PMID 35699863, 2022). "LOX-lysyl oxidase, the enzyme highly overexpressed in tumors derived from CAFs, acts as a collagen crosslinking initiator in several cancers like breast and gastric cancers, ultimately enhancing EMT, cell survival, invasion, drug resistance, and angiogenesis." (PMID 36431766, 2022). "Several different tumors, such as oral, breast, and gastric cancers, overexpress LOX, while increased LOX expression in premalignant host tissue is associated with a higher tumor incidence and burden." (PMID 34815382, 2021). "Our study demonstrates that the HIF1A-AS2/RP11-366L20.2-miR-29c-mediated high expression of LOX can influence the immune status and chemosensitivity and can forecast the poor prognosis of gastric cancer." (PMID 35047494, 2021). "All the results indicate that miRNA-29c is perhaps the most probable upstream regulatory miRNA of LOX in gastric cancer." (PMID 35047494, 2021). "Several publications demonstrate that the mRNA and protein expression of LOX is observably overexpressed in stomach cancer." (PMID 35047494, 2021). "The expression level of LOX affects the immune activity of the tumor microenvironment in gastric cancer." (PMID 34595188, 2021). "Wilcoxon or Kruskal-Wallis test and Logistic regression analysis showed, LOX overexpression is significantly correlated with T-stage progression in gastric cancer." (PMID 34595188, 2021). "With integrated bioinformatics analysis, BGN, LOX, MMP-9, SERPINE1, and TGFB1 proteins have been selected as suitable diagnostic biomarkers for noninvasive to invasive stages of gastric cancer." (PMID 34054953, 2021). "Univariate analysis and multivariate analysis of the correlation of LOX expression with overall survival among patients with gastric cancer." (PMID 34595188, 2021). "Based on the bioinformatics analysis in this study, it was also shown that LOX expression was significantly higher in patients with gastric cancer." (PMID 34054953, 2021). "Univariate Cox regression analysis pointed out that age, T, N, and LOX (all p < 0.05) are all factors affecting the prognosis of gastric cancer." (PMID 34595188, 2021). "We found through Western blotting that compared with the corresponding adjacent tissues, LOX protein was highly expressed in gastric cancer tissues (p = 0.0189)." (PMID 34595188, 2021). "To determine the potential mechanism of LOX expression affecting the prognosis of gastric cancer patients, we performed gene enrichment analysis." (PMID 34595188, 2021). "In this study, we found that among 13 cancer types with differential expression of LOX, 12 tumor types were found with significantly overexpressed LOX, including gastric cancer." (PMID 35047494, 2021). "Western blot and immunohistochemical staining were used to evaluate the expression level of LOX protein in gastric cancer." (PMID 34595188, 2021). "This study evaluated the prognostic role of LOX in gastric cancer (GC) by analyzing the data of The Cancer Genome Atlas (TCGA) and the Gene Expression Omnibus (GEO) dataset." (PMID 34595188, 2021).
gastric cancer (continued). "Another study also claimed that the overexpression of LOX promotes the proliferation, migration, and invasion of gastric cancer cell lines as well as high grade serous ovarian carcinoma." (PMID 34202354, 2021). "The results indicated that the mRNA expression of LOX was markedly higher in gastric carcinoma than that in normal tissues in TCGA + GTEx, GSE26899, GSE54129, and GSE29998 databases." (PMID 35047494, 2021). "Further correlation analysis and survival analysis results indicated that tumor-associated macrophage infiltration probably contributes to the dismal prognosis of patients with high LOX expression in gastric carcinoma." (PMID 35047494, 2021). "In particular, further analysis based on multiple databases further supported the oncogenic effect of LOX in gastric carcinoma." (PMID 35047494, 2021). "LOX induces activation of tumor stromal cells and facilitates the development and progression of gastric carcinoma." (PMID 35047494, 2021). "Then, is there a correlation between LOX expression and chemotherapeutic drug sensitivity of gastric carcinoma?" (PMID 35047494, 2021). "After different concentrations of BAPN (0, 0.1, 0.2, or 0.3 mM) were added to inhibit LOX in gastric cancer cells for 48h, we found that the relative expression levels of PDGFR-α decreased when BAPN concentrations increased." (PMID 31777578, 2019). "We collected fresh cancer specimens from gastric cancer patients who underwent surgery to quantitate the protein expression levels of LOX and MMP-9 in gastric cancer tissues." (PMID 31777578, 2019). "Western blotting was used to quantitate the relative expression levels of platelet derived growth factor receptor (PDGFR) in the BGC-823 gastric cancer cells after LOX inhibition and exogenous LOX addition." (PMID 31777578, 2019). "We constructed a gastric cancer-bearing nude mouse model and used the LOX inhibitor β-aminopropionitrile to inhibit LOX." (PMID 31777578, 2019). "After LOX were inhibited with different concentrations of BAPN in BGC-823 gastric cancer cells, the protein concentrations and enzyme activity levels of MMP-2 and MMP-9 in the culture supernatants were decreased (P < 0.05)." (PMID 31777578, 2019). "In order to understand gastric cancer further, we investigated the effects of LOX on MMP-2 and MMP-9 and its mechanisms in this disease." (PMID 31777578, 2019). "Further, the relative expression of PDGFR in gastric cancer cells was increased with the increase of exogenous LOX, showing a positive dose-dependent manner (rPDGFR-α=0.952, rPDGFR-β=0.953, P<0.05)." (PMID 31777578, 2019). "In gastric cancer tissues with accompanying lymph node metastases, LOX and MMP-2 are positively correlated at the mRNA and protein level." (PMID 31777578, 2019). "Cox regression analysis revealed that positive expression of LOX (P=0.026) was an independent prognostic marker for survival in patients with gastric cancer." (PMID 23425977, 2013). "In the Cox multiple regression analysis, the upregulated expression of LOX was an independent prognostic marker of a worse outcome in gastric cancer patients." (PMID 23425977, 2013). "Ectopic LOX gene expression in gastric cancer cells inhibits tumor formation in nude mice and reduces LOX expression has been reported in many carcinomas." (PMID 24167568, 2013). "Based on the results, LOX mRNA was increased in gastric cancer tissues compared with the adjacent normal mucosa." (PMID 23425977, 2013). "Cultured gastric cancer cells were used to detect whether LOX affected VM formation and analyze the relationship between LOX and PDGFR." (PMID 38434983, 2024). "LOX levels in 49 cases of gastric cancer were determined by immunohistochemistry." (PMID 38434983, 2024). "Relative expression of LOX was also evaluated in 49 cases of gastric cancer by Western blotting." (PMID 38434983, 2024).
gastric cancer (continued). "On the contrary, BAPN concentration was negatively correlated with the VM number of gastric cancer cells, indicating that LOX could promote VM formation in gastric cancer cells." (PMID 38434983, 2024). "It analyzed the correlation between LOX expression and VM formation in gastric cancer tissues." (PMID 38434983, 2024). "Increased expression of GRASLND in gastric cancer tissues has been reported to promote tumor metastasis and proliferation by targeting the miR-30c-2-3p/LOX axis, suggesting a strong correlation between GRASLND, poor prognosis, and advanced disease in SKCM patients." (PMID 39060946, 2024). "The LOX inhibitor BAPN the reduced metastasis of gastric cancer to the liver." (PMID 36980785, 2023). "The integrative analysis combining correlation, differential expression, and survival analysis showed that miRNA-29c might be the best upstream miRNA candidate interacting with LOX in gastric cancer." (PMID 35047494, 2021). "Next, based on the ceRNA hypothesis, the HIF1A-AS2/RP11-366L20.2-miR-29c axis was characterized as the upstream regulatory mechanism of LOX gene overexpression in gastric cancer by combining correlation analysis, expression analysis, and survival analysis." (PMID 35047494, 2021). "Therefore, the function and prognostic significance of LOX in gastric cancer still need to be further explored." (PMID 34595188, 2021). "Targeting inhibition of LOX holds promise as a treatment strategy for gastric cancer." (PMID 35047494, 2021). "Ultimately, we analyzed the correlation of LOX expression with tumor microenvironment, immune cell infiltration, markers of immune cells, immune checkpoints, and chemotherapeutic drug sensitivity to elucidate the biological functions of high LOX expression in gastric cancer." (PMID 35047494, 2021). "Among the identified DEGs, we found that 7 genes (IGFBP7, LOX, NRP1, PRSS3, DPP3, EFNA3, and CD73) were also differentially expressed in tumor tissues and associated with a poor or better prognosis in patients with gastric cancer." (PMID 34659527, 2021). "Increases in LOX, LOXL2 and LOXL4 expression in the ECM of cancer is linked to an increase in focal adhesion kinase (FAK) and Src phosphorylation in colorectal adenocarcinoma, gastric cancer, clear cell renal cell carcinoma and fibroblasts." (PMID 33513979, 2021). "Our research demonstrate that LOX may be potentially applied as a novel prognostic marker and targeting inhibition of LOX holds promise as a treatment strategy for gastric cancer." (PMID 35047494, 2021). "Univariate Cox regression analysis shows that the factors affecting the poor prognosis of gastric cancer are age (p = 0.008114), stage (p = 0.000209), T classification (p = 0.031105), M classification (p = 0.026161), N classification (p = 0.004116), and LOX(p = 0.043712)." (PMID 34595188, 2021). "LOX plays important roles in cancers such as breast cancer (BCa), liver cancer and gastric cancer." (PMID 35003355, 2021). "Also, a closer look at the mechanism of action between semaphorin, LOX, and MMP-9 can reveal new pathways in gastric cancer invasion and its association with the EMT pathway." (PMID 34054953, 2021). "In summary, we can conclude that LOX mRNA and protein are highly expressed in gastric cancer." (PMID 34595188, 2021). "Nevertheless, the detailed biological function of LOX in gastric cancer is still poorly understood." (PMID 35047494, 2021). "Therefore, by combination of correlation analysis, expression analysis, and survival analysis, HIF1A-AS2 and RP11-366L20.2 were considered as the most possible upstream regulatory lncRNAs of the miR-29c/LOX axis in gastric cancer." (PMID 35047494, 2021). "All these data together indicate that the overexpression of LOX potentially facilitates tumor progress and leads to a worse prognosis for patients with gastric cancer by promoting M2 macrophage polarization, which then activates a series of downstream cancer-promoting signaling pathways." (PMID 35047494, 2021).
gastric cancer (continued). "In summary, our results demonstrate that the HIF1A-AS2/RP11-366L20.2-miRNA-29c axis-mediated high expression of LOX results in poor prognosis of gastric cancer by promoting M2 macrophage polarization and tumor immune escape and enhancing drug resistance of cancer cells to chemotherapeutic drugs." (PMID 35047494, 2021). "Furthermore, we also demonstrated that the overexpression of LOX in gastric cancer was positively related to histological grade; TNM stage; T stage; and poor OS, PFS, and PPS." (PMID 35047494, 2021). "Finally, we illustrated that LOX gene overexpression leads to dismal prognosis of gastric cancer, perhaps through promoting M2 macrophage polarization and tumor immune escape and enhancing drug resistance of tumor cells to chemotherapeutic drugs." (PMID 35047494, 2021). "Nevertheless, the specific mechanisms of LOX in stomach carcinoma are still unclear." (PMID 35047494, 2021). "In this study, we demonstrated that LOX is significantly different in 13 types of cancers and may act as a potential therapeutic target, especially in stomach carcinoma." (PMID 35047494, 2021). "Moreover, overexpression of LOX in gastric carcinoma was validated by multiple databases and contributed to the poor overall survival (OS), progression-free survival (PFS) and post-progression survival (PPS) of stomach adenocarcinoma (STAD) patients." (PMID 35047494, 2021). "BAPN (0, 0.1, 0.2, or 0.3 mM) was used to inhibit LOX in gastric cancer cells for 48 hours." (PMID 31777578, 2019). "BAPN was used to inhibit LOX in gastric cancer cells for 48 hours." (PMID 31777578, 2019). "LOX mRNA and protein expression is lower in tumor tissues with lymph node metastasis and deep muscular layer infiltration in upper digestive tract carcinomas, human osteosarcoma tissues, and gastric cancers." (PMID 28036074, 2016). "Indeed, LOX inactivation by methylation has already been demonstrated in gastric cancers as well as colon, lung and ovarian cancer cell lines." (PMID 25790191, 2015). "However, LOX has also been shown to have anti-tumor activity in several cancer types including lung, pancreatic, gastric cancer and nasopharyngeal carcinoma." (PMID 26501565, 2015). "However, in our study, upregulated expression of LOX mRNA and protein has been found in gastric cancer." (PMID 23425977, 2013). "The strong correlations suggested that LOX upregulation may promote tumor invasion and metastasis and that LOX may possibly be used as a biomarker to identify subsets of gastric cancer with a more aggressive phenotype." (PMID 23425977, 2013). "There have been no published studies on the possible association between LOX expression and the clinicopathological features of gastric cancer." (PMID 23425977, 2013). "Both LOX expression and VM formation promoted gastric cancer invasion and metastasis, and the LOX protein in gastric cancer tissues was positively correlated with the number of VM structures, indicating that the higher the expression of LOX, the more VM structures formed in gastric cancer tissues." (PMID 38434983, 2024). "Although various LOX enzymes have been described to have pro-tumor or antitumor roles, and have been targeted in various cancers, the role of SPMs has been studied in inflammation-related cancer, such as colorectal cancer and gastric cancer, and is an emerging field in other cancers." (PMID 35326656, 2022). "Therefore, in order to identify the upstream miRNA candidates that mediated LOX overexpression in gastric cancer, we predicted miRNAs that possibly target LOX in multiple target prediction programs, such as PITA, RNA22, miRmap, microT, miRanda, PicTar, and TargetScan programs." (PMID 35047494, 2021). "Similarly, we found through IHC that LOX protein was highly expressed in gastric cancer." (PMID 34595188, 2021).
gastric cancer (continued). "In addition to this, a recent study in gastric cancer showed a correlation between LOX concentrations present in the serum of patients and the corresponding tissue collected from these patients, which showed significantly increased LOX expression and later stage of disease." (PMID 33513979, 2021). "Hence, we speculate that the overexpression of LOX may result in tumor chemoresistance of gastric cancer by promoting M2 macrophage polarization." (PMID 35047494, 2021). "Our results showed that LOX staining was predominantly present in cytoplasm and nuclei of gastric cancer cell, it has been shown that extracellular LOX was able to enter into the cytosol and became concentrated in the nuclei of smooth muscle cells through an unknown mechanism." (PMID 23425977, 2013). "Several studies have reported changes in LOX, LOXL1, LOXL2, LOXL3, and LOXL4 expression in gastric cancer." (PMID 40906383, 2025). "The expression of BGN, LOX, MMP-9, SERPINE1, and TGFB1 proteins was significantly higher in the samples of gastric cancer patients compared to the healthy people." (PMID 34054953, 2021). "However, the relevance of LOX and immune cells in gastric cancer still remains unclear." (PMID 35047494, 2021). "We found that LOX and MMP-9 expression were positively correlated in the gastric cancer tissues of these 49 patients." (PMID 31777578, 2019). "The relative expression levels of LOX and MMP-9 were 0.052 ± 0.025 and 0.086 ± 0.043, respectively, in the tissues from the 49 gastric cancer patients." (PMID 31777578, 2019). "Immunohistochemistry was used to quantitate the expression levels of LOX and MMP-9 in gastric cancer tissues." (PMID 31777578, 2019). "Immunohistochemistry was used to quantitate the protein expression levels of LOX and MMP-9 in gastric cancer tissues and to analyze their correlation." (PMID 31777578, 2019). "Our previous study has also demonstrated that LOX and MMP-2 expression are positively correlated in tissues from gastric cancer patients." (PMID 31777578, 2019). "In this study, we cultured BGC-823 gastric cancer cells and added different concentrations of BAPN to inhibit LOX activity." (PMID 31777578, 2019). "The MOD of LOX in metastatic gastric cancer tissues was significantly higher than in nonmetastatic gastric cancer tissues (0.0568 ± 0.0244 vs. 0.0334 ± 0.0212), P < 0.05." (PMID 38434983, 2024). "The relative expression of LOX in metastatic gastric cancer tissues was higher than in nonmetastatic gastric cancer tissues (0.33 ± 0.12 vs. 0.22 ± 0.07), P <0.05." (PMID 38434983, 2024). "Therefore, we proposed the existence of hypoxia– LOX+fibroblast–IL6–monocyte– M2 macrophage loop, which induced the progression of gastric cancer and created a specific immunosuppressed state." (PMID 39251966, 2024). "The results revealed that LOX could still induce VM formation in gastric cancer cells when PDGFR was blocked, and LOX concentration was positively correlated with VM formation." (PMID 38434983, 2024). "We speculate that LOX and LOXL2 affect the occurrence and development of gastric cancer by participating in the regulation of extracellular matrix, but further research is still needed." (PMID 35126449, 2021). "Our researches demonstrated that LOX expression has a negative correlation with the sensitivity of commonly used chemotherapeutic drugs for gastric cancer." (PMID 35047494, 2021). "However, our previous research results instead found that LOX and MMP-2 are positively correlated at the mRNA and protein levels in gastric cancer tissues." (PMID 31777578, 2019). "In addition, BGC-823 gastric cancer cells were cultured, then 0.1 mM, 0.2 mM, and 0.3 mM BAPN and 2.5 nM, 5 nM, and 10 nM LOX were added to treat BGC-823 cells." (PMID 31777578, 2019). "However, our previous study found that expression of LOX and MMP-2 are positively correlated in gastric cancer tissues, and they play synergistic roles in promoting the invasion and metastasis of gastric cancer." (PMID 31777578, 2019).